GNS (glucosamine (N-acetyl)-6-sulfatase)
Description:
Hydrolyzes 6-sulfate groups in N-acetyl-d-glucosaminide units of heparin sulfate and keratan sulfate.
Synonyms: G6S
Tractability: Antibody: its Gene Ontology location is reachable by antibodies, with high confidence; UniProt predicts a signal peptide or a membrane-spanning region. PROTAC: ubiquitination databases record sites on it; its protein half-life has been measured.
Gene: Protein-coding gene on chromosome 12 (64,713,442 to 64,759,446, reverse strand). Ensembl gene ENSG00000135677.
Subcellular location: Lysosome
Pathways (Reactome):
Disease: MPS IIID - Sanfilippo syndrome D
Immune System: Neutrophil degranulation
Metabolism: Keratan sulfate degradation
Vesicle-mediated transport: Lysosome Vesicle Biogenesis
Gene Ontology:
Molecular function: N-acetylglucosamine-6-sulfatase activity; protein binding; sulfuric ester hydrolase activity; glycosaminoglycan binding; sulfate binding
Biological process: heparan sulfate proteoglycan catabolic process; glycosaminoglycan catabolic process; glycosaminoglycan metabolic process; keratan sulfate proteoglycan catabolic process
Cellular component: azurophil granule; extracellular exosome; azurophil granule lumen; extracellular region; ficolin-1-rich granule lumen; lysosomal lumen; lysosome
Genetic constraint (gnomAD): Loss-of-function variants: 6 observed, 7.52 expected, observed/expected ratio (o/e) 0.8, 90% interval 0.44 to 1.54. That is too few expected variants to judge how well the gene tolerates losing a copy. Missense variants: 152 observed, 174.33 expected, observed/expected ratio (o/e) 0.87, 90% interval 0.76 to 1. Synonymous variants: 84 observed, 70.38 expected, observed/expected ratio (o/e) 1.19, 90% interval 1 to 1.43.
Gene-disease validity (ClinGen):
ClinGen rates the evidence that GNS causes each of these diseases.
mucopolysaccharidosis type 3D (autosomal recessive): Definitive. A rare autosomal recessive lysosomal storage disease caused by deficiency of the enzyme N-acetylglucosamine-6-sulfatase.
Homologues: Orthologues: chimpanzee GNS (100% identical), macaque GNS (99% identical), dog GNS (95% identical), guinea pig GNS (93% identical), rabbit GNS (93% identical), pig GNS (91% identical), mouse Gns (90% identical), rat Gns (89% identical), tropical clawed frog gns (74% identical), zebrafish gnsa (69% identical), Drosophila melanogaster CG18278 (40% identical), Drosophila melanogaster CG30059 (40% identical), and 3 more. Paralogues in human: SULF2 (42% identical), SULF1 (39% identical), ARSL (20% identical), STS (20% identical), GALNS (20% identical), ARSD (19% identical), ARSH (19% identical), ARSF (19% identical), SGSH (18% identical), ARSA (18% identical), ARSG (17% identical), ARSJ (17% identical), and 4 more.
Diseases named in the same sentence as GNS in open-access papers:
GNS is named in the same sentence as 29 diseases in open-access papers, as found by Europe PMC text mining. Sharing a sentence is not in itself a finding about the gene and the disease. The quoted sentences say what the papers report.
mucopolysaccharidosis type 3D (5 papers, 2012 to 2025). "Mutations in the GNS gene cause mucopolysaccharidosis type IIID (Sanfilippo syndrome D; OMIM phenotype 252940)." (PMID 26023928, 2015).
glioma (4 papers, 2020 to 2023). A benign or malignant brain and spinal cord tumor that arises from glial cells (astrocytes, oligodendrocytes, ependymal cells). "On the other hand, the elevated expression of GNS and ATAD3A/B is associated with poor survival rates in liver cancer, while high expression of GNS in glioma and ovarian cancer is a marker of poor prognosis." (PMID 37775701, 2023). "This study identified the MAGs of IDH wild-type glioma and the prognostic model was constructed by genes including GNS, LBH and SCARA3." (PMID 33198677, 2020).
diabetes (3 papers, 2020 to 2024). "For instance, target genes (FLAD1, SLFNL1, GNS, FBXL18, CYP2B7P) are commonly upregulated genes in metabolic-induced HCC and are associated with risk factors, such as diabetes, obesity, and other metabolic syndromes." (PMID 32228601, 2020). "Notably, three proteins (CPQ, CTSB, and GNS) were common among all four urinary signatures, and they were consistently excreted at higher rates in diabetes." (PMID 32453760, 2020).
mucopolysaccharidosis type 3 (3 papers, 2022 to 2024). A lysosomal disease characterized by progressive neurocognitive decline, severe intellectual deterioration, loss of functional abilities, and premature death. "Mucopolysaccharidosis type III (MPS III, Sanfilippo disease), is a group of 4 autosomal recessive LSDs caused by pathogenic variants in SGSH, NAGLU, HGSNAT and GNS, respectively." (PMID 35646708, 2022). "The rarest subtypes of mucopolysaccharidosis type III, namely subtype C [OMIM:252930] and D [OMIM:252940], are both hyper-rare AR LSDs with an unknown prevalence, caused by genetic mutations of two different genes: the HGSNAT gene (8p11.2-p11.1) and the GNS gene (12q14.3), respectively." (PMID 37239976, 2023).
lysosomal storage disease (2 papers, 2024). A metabolic disorder caused by mutations in proteins critical for lysosomal function, including lysosomal enzymes, lysosomal integral membrane proteins, and proteins involved in the post-translational modification and trafficking of lysosomal proteins. "MPS III is an autosomal recessive lysosomal storage disease caused mainly by missense variants in the NAGLU, GNS, HGSNAT, and SGSH genes." (PMID 38802532, 2024). "Although uncommon, abnormalities in the GNS gene can result in a rare condition known as lysosomal storage disorder." (PMID 38245687, 2024).
rheumatoid arthritis (2 papers, 2022). A chronic, systemic autoimmune disorder characterized by inflammation in the synovial membranes and articular surfaces. "Another example of molecular mimicry involves the rheumatoid arthritis (RA)-relevant autoantigens N-acetylglucosamine-6-sulfatase (GNS) and filamin A (FLNA)." (PMID 35572569, 2022). "Known glycan self-antigens are MOG for MS, Myelin oligodendrocyte glycoprotein antibody-associated disease (MOGAD) and NMO/NMOSD; MAG for human demyelinating neuropathy; GM1, GD1a, GT1a and GQ1b for GBS; the latter also for BBE; and N-acetylglucosamine-6-sulfatase (GNS) for Rheumatoid Arthritis." (PMID 35806376, 2022).
cirrhosis of the liver (1 paper, 2014). "The miR-17-5p target GNS (glucosamine (N-acetyl)-6-sulfatase) that metabolises glucosamine sulphate has been implicated in hepatocellular dysplasia, cirrhosis of the liver and hepatic fibrosis." (PMID 24428929, 2014).
Ewing sarcoma (1 paper, 2022). A small round cell tumor that lacks morphologic, immunohistochemical, and electron microscopic evidence of neuroectodermal differentiation. "Specifically, we found upregulation of enzymes involved in the catabolism of heparan sulfate proteoglycans (including SGSH, GNS, HS3ST4, HS3ST1, HS2ST1, and HS6ST1) in human Ewing sarcoma." (PMID 35285802, 2022).
influenza (1 paper, 2017). An acute viral infection of the respiratory tract, occurring in isolated cases, in epidemics, or in pandemics; it is caused by serologically different strains of viruses (influenzaviruses) designated A, B, and C, has a 3-day incubation period, and usually lasts for 3 to 10 days. "Glucosamine (N-acetyl)-6-sulfatase (GNS) is a lysosomal enzyme found in all cells and has been shown to be perturbed following yellow fever and live-attenuated influenza vaccine." (PMID 28137280, 2017).
mucopolysaccharidosis (1 paper, 2016). A group of autosomal recessive or X-linked inherited lysosomal storage disorders affecting the metabolism of mucopolysaccharides, resulting in the accumulation of mucopolysaccharides in the body. "A homozygous splice-site-mutation in the GNS gene could be found, compatible with mucopolysaccharidosis–Sanfillipo syndrome (type IIID)." (PMID 27512882, 2016).
rheumatic diseases (1 paper, 2017). "N-Acetyl-glucosamine-6-sulfatase (GNS) and filamin A (FLNA) were identified as autoantigens that produce responses from both T and B cells, in over 50% of RA patients, but not in healthy controls or patients with other rheumatic diseases." (PMID 28948174, 2017).
type 1 diabetes (1 paper, 2020). "Interestingly, all enzymes involved in keratan sulfate degradation (ie., GALNS, GLB1, GNS, HEXA, and HEXB) were elevated in urines from youths with type 1 diabetes, compared to non-diabetic youths." (PMID 32453760, 2020).
tumor (5 papers, 2012 to 2023). "All these data are consistent with the pivotal role of YAP in our experimental model, in which HPV16E7, through its interaction with GNS and the associated morpho-functional alterations of the microfilament system, promotes tumor cell invasion capability and aggressiveness." (PMID 33477952, 2021). "The association between a GNS expression signature and survival is consistent with the hypothesis that a cancer stem cell component drives tumor growth." (PMID 23046790, 2012). "As expected, the mean tumor volume in the Adr-GNs+siRap2b-GNs treated mice was reduced by 78%, demonstrating a significant improvement in the therapeutic efficacy over the Adr-GNs group (P < 0.01)." (PMID 28423503, 2017). "Substantial CNV deletions were observed in PABPC5, MSH6, IFI16, GNS, ERCC4, BRCA1 and ACACB, while substantial CNV amplification was observed in most tumour types for the remaining genes." (PMID 37660060, 2023).
GNS also shares sentences with these, for which no sentence is quoted: infection (3 papers); cancer (2); fungal infection (1); Hepatic fibrosis (1); legionellosis (1); leishmaniasis (1); Lipid storage disease (1); liver cancer (1); metabolic syndrome (1); Neonatal sepsis (1); Obesity (1); ovarian carcinoma (1); Sanfilippo syndrome type A (1); Sanfilippo syndrome type B (1); Sepsis (1); yellow fever (1).